RUNX1 (RUNX family transcription factor 1)
Diseases named in the same sentence as RUNX1 in open-access papers (continued):
Sharing a sentence is not in itself a finding about the gene and the disease.
cancer (continued). "While the myeloid-B and myeloid-T phenotypes shared some cancer gene mutations in common, the pattern of somatic mutations differed between the two phenotypes, with significant differences in the frequency of NOTCH1 and RUNX1 mutations." (PMID 29991687, 2018). "We examined the mechanisms by which Runx1 regulates EMT in cancer progression." (PMID 28407681, 2017). "Moreover, the present data provide new insights regarding the ability of estrogens to trigger the GPER/miR144/Runx1 transduction pathway toward the stimulation of cancer progression." (PMID 26030000, 2015). "Importantly, we detected that p‐Runx1 was progressively induced in the macrophages undergoing cancer condition‐driven MMT on the BMDMs under LLC conditioned medium (LLC‐CM) stimulation in vitro, suggesting a potential role of Runx1 in the regulation of MMT development in NSCLC." (PMID 37967345, 2024). "CDKN2A, IKZF1, ETV6, RUNX1, and FLT3 were the top genes mutated in leukemias, while somatic alterations in ALK, NF1, and PTEN primarily occurred in solid tumors, suggesting that the driver alterations are either common to cancer (e.g., cell cycle) or specific to pediatric cancer histotype." (PMID 36845394, 2023). "Although decreased levels of RUNX1 expression are associated with metastasis in a wide range of cancers, including those arising from the lung, breast, prostate, colorectal, uterus, and ovary, increased RUNX1 expression levels might also be involved in oncogenesis in certain types of cancer." (PMID 36831211, 2023). "Therefore, changes in RUNX1 expression are also closely related to cancer." (PMID 37760803, 2023). "Pro-fibrotic fibroblasts were transcriptionally similar to cancer associated fibroblasts and expressed high levels of collagens and periostin (POSTN), thymocyte differentiation antigen 1 (THY-1), and endothelin receptor A (EDNRA) predicted to be driven by a RUNX1 gene regulatory network." (PMID 36747878, 2023). "Thus, we speculate that at least certain cancer-associated mutations in RUNX1B may exhibit the capacity to alter drug binding, and thereby facilitate drug binding to the RUNX1 protein." (PMID 36090034, 2022). "While ts-112 and RUNX family transcription factor 1 (RUNX1) were negatively correlated in BC cells versus normal breast epithelial cells, RUNX1 may exert its cancer-suppressive function by inhibiting ts-112 to prevent over-proliferation of normal breast epithelial cells." (PMID 35658952, 2022). "However, many studies have revealed that RUNX1 has cancer-promoting properties in solid tumors." (PMID 36429115, 2022). "However, RUNX1 expression also decreased in several cancer datasets from the GenT2 database." (PMID 35534796, 2022). "Additionally, an increased level of RUNX1 is associated with the immune infiltrate levels of CAFs and the activation of oncogenic signaling pathways in human cancers, which could be the potential mechanism by which RUNX1 affects patient outcomes." (PMID 35534796, 2022). "Moreover, RUNX1 expression may influence patient prognosis by activating oncogenic signaling pathways in human cancers." (PMID 35534796, 2022). "Therefore, it is reasonable to speculate that RUNX1 expression may influence patient prognosis by activating oncogenic signaling pathways in human cancers." (PMID 35534796, 2022). "Interestingly, RUNX1 expression is uniformly higher in the cancer cells adjacent to liver tissue." (PMID 34376784, 2021). "In addition, RUNX1 mainly participated in peroxisome, microRNA and proteoglycans in cancers." (PMID 34294773, 2021). "Interestingly, replication timing changes common to all cancer specimens included the region next to the Runt-related transcription factor 1 (RUNX1) locus, a common leukemic translocation site though only some specimens displayed the actual translocation itself." (PMID 28587102, 2017).
cancer (continued). "Several target genes regulated by miR-215 in different cancers have been reported, and we observed that RUNX1 is a direct target of miR-215 as evidenced by the fact that ectopic expression of miR-215 reduced luciferase activity of the RUNX1 promoter and miR-215 downregulated RUNX1 expression." (PMID 26716895, 2016). "Besides its developmental determination role, RUNX1 is involved in malignant tumor formation." (PMID 26697518, 2015). "Current research suggests the crucial involvement of RUNX1 and EPHA2 in angiogenesis and the invasion of cancer cells." (PMID 39797421, 2025). "In 21q22, we detected amplification of five cancer genes, including the transcription factors ERG and RUNX1 and the RNA binding protein U2AF1." (PMID 39421445, 2024). "Mechanistically, RUNX1 exerts direct regulation over MUC13, activating the Wnt/β-catenin pathway, a critical mediator in cancer progression and EMT." (PMID 39309442, 2024). "To note, the antitumor effect of systemic inhibition of Runx1 was better than the macrophage specific strategy in vivo, implying additional Runx1‐dependent mechanisms beyond MMT contributing to the cancer progression which can be further investigated." (PMID 37967345, 2024). "As RUNX1 can bind to USP31, to further investigate the interaction by searching for inhibitors against both by Genomics of Drug Sensitibity in Cancer (GDSC)." (PMID 38886545, 2024). "The analysis showed that TWIST1, RUNX1, CEBPA, and RELA were upregulated in carcinoma samples compared with normal renal tissues, whereas HIF1A was downregulated." (PMID 38724670, 2024). "Meanwhile, RUNX1 can act as a key factor in the regulation of EMT and further promote the invasion and metastasis of cancer cells by EMT." (PMID 37760803, 2023). "RUNXs belong to a family of metazoan transcription factors, and there are three main RUNX in mammals (namely, RUNX1, RUNX2, and RUNX3), which are the major regulators of development and often deregulated in human cancers." (PMID 36321611, 2023). "RUNX1-unmutated MDS patients were protected by DNA damage and cellular senescence, which emerged as a critical anticancer barrier to cancer progression." (PMID 37190015, 2023). "Next, we identified significantly enriched KEGG (Pathways in cancer and PI3K/Akt signaling pathway) and GO (GO:0000122, GO:0045944 and GO:0045893) terms, and identified eight genes (EDN1, CCND1, MYB, MYC, RUNX1, ITGA6, IL6 and FGF2." (PMID 36978140, 2023). "In conclusion, RUNX1 binds target genes (VEGF and COL4A1) and involves signalling pathways of cancer proliferation, metastasis, and angiogenesis." (PMID 37759525, 2023). "Our results provide proof for the feasibility of targeting RUNX1/ETO in a pre-clinical setting and support the further development of siRNA-LNPs for the treatment of fusion gene-driven malignancies." (PMID 36823395, 2023). "In contrary to RUNX1 and RUNX3, RUNX2 promoted cancer cell recruitment and adhesion in bone and further facilitated bone colonization." (PMID 36092942, 2022). "Taken together, these data suggest the influence of cancer cells on neutrophil infiltration in CRCLM lesions, and RUNX1 plays a key role in this process." (PMID 36330498, 2022). "By observing the heat map showing the CNV situation, we found that RUNX1, SCG2, and BTG1 have high heterozygous amplification in various cancers, including ACC, TGCT, and UCS." (PMID 35498539, 2022). "High significance of the runt-related transcription factor family (RUNXs), including RUNX1, RUNX2, and RUNX3, which are involved in developmental processes, immune response, and cancer, was also identified." (PMID 35629968, 2022).
cancer (continued). "For the first time, we used TCGA, Oncomine, and cBioPortal to analyze the RUNX gene family (RUNX1, RUNX2, and RUNX3) in 33 distinct human cancer types and matched normal tissues." (PMID 35522574, 2022). "While the role of Runx1 during kidney development is unknown, it is activated in kidney during injury and repair where it may contribute to several disease processes, including cancer, in which it may collaborate with Runx2 to drive EMT associated with worse outcomes." (PMID 34111109, 2021). "Herein, we identified RUNX1 as a key player in vessel co-option by regulating motility and EMT in cancer cells." (PMID 34376784, 2021). "Independent confirmation of the significance of CCND2 came from the Cancer Dependency Map project, where genome-wide RNAi screens identified CCND2 as an essential gene in the two 2 RUNX1/RUNX1T-expressing AML cell lines within a total of 501 cancer cell lines." (PMID 33217477, 2021). "To find out if RUNX1 can modulate TGFβ1 function in these processes, we performed various in vitro experiments and treated cancer cells with either recombinant TGFβ1 or co-cultured with hepatocyte (IHH) cells, upon RUNX1 inhibition." (PMID 34376784, 2021). "LncRNA-NEF overexpression led to inhibited expression of RUNX1 in cells of IHCC cell lines and inhibited cancer cell migration and invasion." (PMID 31015363, 2019). "Since HMGA2 is an important gene expression modulator in cancer, we proposed that, through regulation of HMGA2, miR-302a-5p/367-3p also indirectly influences RUNX1 protein expression." (PMID 29391048, 2018). "Core-analysis of the altered miRNAs identified top scoring networks of interacting miRNA, which interplay through several genes and molecules known to be involved in cancer and EMT including STAT3, CEBP/β, RUNX1, VEGF and TGF-β." (PMID 28423669, 2017). "Several cancer-related genes such as STK11, SMARCA4, and RUNX1 were located within the HMA-resistance-specific CNAs." (PMID 28052028, 2017). "Many of these genes, such as AKT1, RUNX1 and LIMA1, are known to be involved in cancer and related processes." (PMID 25884336, 2015). "Taken together, our results suggest that in SkBr3 and HepG2 cancer cells E2 and G-1 through GPER induce miR144 expression which negatively regulates the levels of its target gene Runx1." (PMID 26030000, 2015). "In particular, four genes within pathways in cancer were differentially expressed in the same direction under all the three conditions, including HSP90B1, ARAF, and RUNX1, being downregulated, and CDK4, being upregulated under these three manipulations." (PMID 25007077, 2014). "Four correlations of gene expression, NFKB2-PTGS2, JUN-MMP1, RUNX1-CEBPA, and JUN-FIGF, were identified in pathways in cancer." (PMID 24579087, 2014). "RUNX1 is a member of the core binding factor (CBF) family of proteins, which are known to have roles in embryonic development, proliferation, differentiation, and cancer." (PMID 41214140, 2026). "Since super-enhancers (SEs) have been shown to drive high levels of oncogenic gene expression to maintain cancer cell survival, we next set out to determine whether JMJD1C and RUNX1 regulate gene expression by binding to SEs." (PMID 39450904, 2025). "RUNX1's pivotal role in modulating EMT and cellular stemness, which significantly related to the invasive characteristics of tumors, was critical for understanding its impact across different cancer types." (PMID 39309442, 2024).
cancer (continued). "In conclusion, in this study, we demonstrated that the RUNX1 transcription factor might act as an oncogene and a prognostic biomarker for COAD promotes cancer progression in COAD by activating target gene transcription." (PMID 38886545, 2024). "In this study, we showed that Runx1 inhibitor, Ro5‐3335, induced no side effect on the cancer‐bearing mice." (PMID 37967345, 2024). "RUNX1-ETO, the mutant and infusion form of the RUNX1 protein, has been identified in cancer." (PMID 36814822, 2023). "After treated with Ro5-3335, a RUNX1-CBFβ interaction inhibitor, the phosphorylation level of EGFR (Tyr1068), STAT3 (Tyr705) and AKT (Ser473, Thr308) were significantly decreased in control cancer cell lines (SKOV3, OVCAR3) and generated the similar pattern that RUNX1 knockdown induced." (PMID 38057816, 2023). "Unlike RUNX1, which is frequently mutated in human cancer, the RUNX3 gene is often transcriptionally silenced in cancer by CpG island DNA methylation or through EZH2-dependent H3K27me3 (histone H3 lysine 27 trimethylation) modification in the RUNX3 promoter." (PMID 37190015, 2023). "The first were tightly regulated, through MELK, BRCA2, KIF14, BUB1, and TOP2A, by five TFs (NFE2L3, RUNX1, RUNX2, BHLHE40, and the aging cancer-specific SOX11), two LncRNAs (ST7OT1 and CDKN2BAS), and four miRNAs (miR-21-5p, miR-363-3p, miR-873-5p, and miR-138-1-3p)." (PMID 37191407, 2023). "Therefore, RUNX1 and STAT3 inhibitors are also expected to have therapeutic value in the treatment of mTORC1-related cancers." (PMID 37760803, 2023). "The detected cancer genes NOTCH1 and RUNX1 could possibly influence the RUNX3 signaling pathway and could be meaningful for metastases formation." (PMID 38010391, 2023). "In contrast to RUNX1 and RUNX3, which may function as oncogenes or tumor suppressors, RUNX2 is mostly overexpressed and oncogenic in human cancer." (PMID 37190015, 2023). "Interestingly, RUNX1 accounts for the role of oncogene in the EMT and metastasis of several types of cancer." (PMID 37367670, 2023). "Firstly, we confirmed the efficiency of RUNX1 knockdown in HT29 and SW620 cancer cells." (PMID 36330498, 2022). "In addition, the related pathways of RUNX1 and EWSR1 include transcriptional misregulation in cancer." (PMID 35057728, 2022). "We noticed lower levels of Ang1 in CRCLM lesions generated by RUNX1-silenced HT29 cancer cells regardless of their histopathological growth patterns." (PMID 36330498, 2022). "On the other hand, in transcriptional misregulation in the cancer signaling pathway, only MYCN expression was notably decreased, and the expression of 20 genes, including GADD45A, CXCL8, JMJD1C, RUNX1, and H3C14, was significantly increased in NHEKs upon HPV8 E7 expression." (PMID 35665406, 2022). "Finally, we assessed the protein levels of RUNX1 in the tissues based on the results from the HPA database and found that most of the cancer tissues were moderately positive for granular cytoplasm." (PMID 35534796, 2022). "Our data suggest that mutations of RUNX1 in OAC, and perhaps in other carcinomas, are change-of-function, rather than simple gain or loss-of-function." (PMID 35396535, 2022). "The absence of RUNX1 in the co-cultured cancer cells resulted in lower expression of TGFβ1 in hepatocytes." (PMID 34376784, 2021). "In the present study, we report that RUNX1 acts as an oncogene in CRC by activating the Hedgehog signaling pathway to promote cancer cell proliferation and regulating ABCG2 expression to reduce the sensitivity of cancer chemotherapy." (PMID 34659526, 2021). "To test this hypothesis, we knocked down RUNX1 in HT29 and SW620 cancer cells followed by co-culturing with hepatocytes (IHH cells)." (PMID 34376784, 2021). "We also noticed a reduction in the size and number of lesions in the absence of RUNX1 in injected cancer cells." (PMID 34376784, 2021).
cancer (continued). "CircRUNX1, as a circRNA originating from RUNX1 and abundantly expressed in PTC, may be partly involved in this cancer-promoting process." (PMID 33479208, 2021). "Moreover, HCC45 was enriched for targets of several well-known cancer-related transcription factors such as MYC and RUNX1 and were functionally connected as a group (protein–protein interaction network enrichment: P < 1e−16)." (PMID 30626396, 2019). "RUNX1 and TWIST1 and patients’ gender didn’t show a correlation with cancer-specific survival." (PMID 31655611, 2019). "This study elucidates the ability of cells expressing RUNX1 fusion oncoproteins to evade RUNX growth suppressive potential and supports the predictive value of insights from primary cell systems for the in vivo behavior of mutant cancer genes." (PMID 29052866, 2018). "Indeed, Runx1 stimulates Stat3 signaling in three epithelial cancer cell types through the transcriptional repression of a Stat3 inhibitor, SOCS3, which triggers cancer cell growth." (PMID 30026553, 2018). "Therefore, similar to other renowned cancer related proteins (e.g. E2Fs, p21, GADD45A, MYC and RUNX1), Trib2 obeys the Goldilocks principle in cancer biology; too little or too much are both pro-tumorigenic." (PMID 29670085, 2018). "To investigate whether the HMA-resistance-specific CNAs influence gene expression, we assayed the expression of 8 cancer-related genes by quantitative reverse transcription PCR (RT-qPCR) including BCL9, ARNT, ABL2, STK11, TCF3, SMARCA4, RUNX1, and U2AF1." (PMID 28052028, 2017). "Finally, several TF inhibitors are currently in clinical trials (e.g., SY-1365, a CDK7 inhibitor altering gene expression, including Runt-related transcription factor 1 (RUNX1) expression in advanced solid tumors) or in use (e.g., the estrogen receptor inhibitor Tamoxifen) to treat cancers." (PMID 40178639, 2025). "Altogether, these results suggest that the RUNX1 expression could promote CC via deregulation of expression of genes involved in key signaling pathways to CC, such as the Wnt signaling pathway, cGMP-PKG signaling pathway and Pathways in cancer." (PMID 41020879, 2025). "Molecular aberrations that were shared in at least one P/X pair and that were previously recognized to have deleterious effects in human cancers included CHEK2 [K416E; 415S (SNP)], EGFR (158N), ATM (P1054R), STK11 (D194N), PIK3CA (E545K), KIT (798I; M541L), and RUNX1 (L56S)." (PMID 34714554, 2022). "In summary, RUNX1 expression may have positive or negative effects on the clinical outcomes of different cancers." (PMID 35534796, 2022). "However, RUNX1 was found to have a negative overall effect on cancer survival according to the GEPIA database." (PMID 35534796, 2022). "To examine whether the absence of RUNX1 in the cancer cells affects cancer cell-driven hepatocyte modifications in vivo, we stained specimens that were generated from our previous publication with PARP-1, ARP2/3, or E-cadherin antibody." (PMID 35267627, 2022). "Notably, RUNX1 had a negative overall effect on cancer (OS: total log-rank P = 0, HR = 1.4; DFS: total log-rank P = 0.29, HR = 0.96)." (PMID 35534796, 2022). "Our results suggest that RUNX1 expression is dysregulated in almost all tumors and may have positive or negative effects on the clinical outcomes of patients with cancer." (PMID 35534796, 2022). "In conclusion, this study revealed that RUNX1 plays an essential role in the development of replacement pattern vessel co-opting CRCLM lesions through regulation of its downstream molecules including ARP2/3, vimentin, and TSP1, which facilitate cancer cell motility." (PMID 34376784, 2021).